ERG (ETS transcription factor ERG)
Diseases named in the same sentence as ERG in open-access papers (continued):
Sharing a sentence is not in itself a finding about the gene and the disease.
prostate carcinoma (continued). "CK18 was recently detected in the circulation of patients with gastric and colorectal cancer, and linked to a particular subtype of prostate cancer that aberrantly expresses p63, lacks the androgen receptor (AR) and harbors rearrangements of the ERG gene." (PMID 25857301, 2015). "For example, CRISP3 overexpression is strongly associated with PTEN deleted ERG positive prostate cancer." (PMID 25825985, 2015). "Positive HOOK3 immunostaining was linked to TMPRSS2:ERG rearrangement and ERG positivity in prostate cancers." (PMID 26230842, 2015). "The striking limitation of the prognostic impact of SOX9 loss to the subset of ERG-positive cancers with PTEN deletions provides further evidence for the existence of clinically relevant molecularly distinct subgroups of prostate cancers." (PMID 26030748, 2015). "Herein, we report that in leukemia, ERG overexpression causes molecular characteristics that are strikingly similar to the ERG-associated signaling networks in prostate cancer." (PMID 24504051, 2014). "The upregulation of some Wnt pathway members was observed in ERG-positive prostate cancers, and it has been shown that knockdown of the ERG gene in VCaP prostate cancer cells causes an activation of cell adhesion and expression changes in Wnt signaling." (PMID 25148538, 2014). "ERG was recently shown to inhibit luminal and neuroendocrine differentiation in a transgenic prostate cancer mouse model, suggesting that ERG can be linked to de-differentiation of cancer cells." (PMID 25629002, 2014). "Tumors expressing ERG was associated with an increased relative risk for prostate cancer specific death in a univariate Cox regression analysis." (PMID 24505269, 2014). "At protein levels ERG is detected as a nearly uniformly overexpressed protein in over 60% of prostate cancer patients as revealed by the diagnostic evaluation of ERG oncoprotein detection in prostatic carcinoma." (PMID 24418414, 2014). "There is a direct evidence suggesting that a deubiquitinase namely ubiquitin-specific peptidase 9, X-linked (USP9X) can regulate the ERG protein expression in prostate cancer VCaP cells." (PMID 24739220, 2014). "We have described current research of the cell-type-specific genome-wide binding patterns of ERG and regulating mechanisms by TMPRSS2-ERG encoded fusion products in prostate cancer cells." (PMID 24739220, 2014). "In the current study, we found that ERG rearrangement was significantly associated with prostate cancer-related death in Chinese PCa patients." (PMID 24516518, 2014). "Somatic mutations in prostate cancer gives rise to chromosomal rearrangements that juxtapose the coding sequence of an ETS family transcription factor gene (most commonly ERG or ETV1) next to the androgen –related TMPRSS2 promoter." (PMID 24063260, 2013). "Taken together our data demonstrate that ERG-rearrangements in prostate cancer are associated with a variety of transcriptional changes in cancer cells including the expression of metabolic sensors like NPY." (PMID 23390522, 2013). "We observed, for the first time, that ERG rearrangements are possibly associated with metabolic changes in prostate cancer cells." (PMID 23390522, 2013). "Accumulation of ERG was also found to be associated with an altered DNA methylation pattern in prostate cancer cells." (PMID 23555854, 2013). "In conclusion, we report here that overexpression of ERG transcription factor in TMPRSS2:ERG-positive prostate cancer induces a loss of DNA methylation at the TDRD1 promoter-associated CpG island." (PMID 23555854, 2013). "In 3,349 ERG positive prostate cancers, these associations were largely inexistent, although there was still a weak association between MTC02 staining and high Gleason grade (p = 0.008)." (PMID 24261794, 2013). "We have previously shown that induction of E-cadherin expression is associated with reduced cell proliferation in ERG positive VCaP prostate cancer cells." (PMID 23251544, 2012).
prostate carcinoma (continued). "ETS gene fusions promote multiple signaling pathways associated with cancer formation and progression, and ectopic ERG oncogene expression has been associated with a specific molecular signature in prostate cancer." (PMID 22761906, 2012). "The scarce studies that have addressed this issue have described only a limited number of genes associated with ERG overexpression in prostate cancer." (PMID 21814574, 2011). "According to long term clinical studies performed on a large cohort of patients, it seems that TMPRSS2/ERG expression is associated with a more aggressive form of prostate cancer." (PMID 21747944, 2011). "Previously it was reported that the majority of prostate cancers have a chromosomal rearrangement as a result of fusion of gene encoding TMPRSS2 with transcription factor ERG." (PMID 24213111, 2011). "The top-most differentially expressed genes and their associations with ERG over-expression were technically validated by quantitative real-time PCR and biologically validated in an independent series of 200 prostate carcinomas." (PMID 21814574, 2011). "Several studies suggest that TMPRSS2:ERG fusion prostate cancer contribute to a more aggressive cancer phenotype, which is associated with higher tumor stage and prostate cancer-specific death." (PMID 24281166, 2010). "In the current study 41 of 46 ERG rearranged prostate cancers were lethal; the unadjusted odds ratio for lethal disease associated with ERG rearrangement status was 7.2 (95% CI 2.8-19.0)." (PMID 20233430, 2010). "TMPRSS2:ERG gene fusions have been associated with aggressive prostate cancer in a transgenic mouse model, detected in distant metastasis and also linked with aggressive prostate cancer phenotypes in humans." (PMID 20598135, 2010). "It has been recently reported that ERG fusion is associated with lethal prostate cancer in Scandinavian men treated with watchful waiting." (PMID 18846227, 2008). "We conducted a survival analysis to determine the prognostic significance of the presence of the TMPRSS2:ERG fusion gene on the risk of prostate cancer recurrence, adjusting for the established prognostic factors." (PMID 17971772, 2007). "To examine further these associations, we sought the presence of TMPRSS2:ERG gene fusion in 165 frozen prostate cancer samples from patients who underwent radical prostatectomy for localised prostate cancer." (PMID 17971772, 2007). "Our findings indicate that PTEN and ERG biomarkers may have potential utility in assessing risk and guiding personalized treatment strategies in prostate cancer patients following radical prostatectomy." (PMID 40863209, 2025). "Conversely, certain experiments indicate that NEPC undergoes transdifferentiation from prostatic adenocarcinoma, supported by the detection of prostate cancer-specific mutations (for example, ERG rearrangements) and gene amplifications (for example, AURKA and MYCN) in both subtypes." (PMID 38534956, 2024). "Olaparib has been shown to reduce the potential of invasion in ERG-positive prostate cancer cell lines through the inhibition of invasion-associated genes, for example, EZH2, which may provide new molecular therapeutic targets." (PMID 37686423, 2023). "CAG repeats may be associated with TMPRSS2: ERG fusion-positive prostate cancer, but may be protective against PC in China." (PMID 36824501, 2023). "The findings of this study suggest that a distinct group of young patients with aggressive prostate cancer is frequently associated with TMPRSS2:ERG fusions, while exhibiting a lower likelihood of harboring mutations in other genes, such as AR, SPOP, and ASXL1." (PMID 37511059, 2023). "Conversely, in a different study, TMPRSS2:ERG fusion detected by RNA sequencing in prostate cancer samples was associated with a lower lymphocytic infiltration, a finding that could potentially interfere with the biology of the tumor immune response." (PMID 37511059, 2023).
prostate carcinoma (continued). "Lately, ERG has been associated with prostate cancer through gene fusion to TMPRSS247." (PMID 35831333, 2022). "Kohvakka and colleagues further demonstrated that the ERG- and AR-regulated lncRNA EPCART (ERG-positive PC-associated androgen responsive transcript) is functionally relevant for prostate cancer, as knockout of EPCART reduces migration and proliferation of LNCaP cells." (PMID 33634124, 2021). "In addition, VPA and TSA were able to repress the transcription of ERG, which its overexpression has been associated with poor prognosis and unfavorable clinical outcomes in prostate cancer patients." (PMID 32760400, 2020). "TDRD1 is closely associated with ERG overexpression in primary prostate cancer." (PMID 32828126, 2020). "Besides providing advanced evidence for the inverse association between diabetes and prostate cancer, this study is the first to report associations between diabetes and ERG/PTEN defined prostate cancers." (PMID 32467600, 2020). "We propose multiplexing this assay with our previously identified aggressive disease markers, as well as existing clinical biomarkers such as Prostate cancer antigen 3 (PCA3), TMPRSS2:ERG (T2:ERG), etc. to assist in the management of prostate cancer especially in low‐risk cohorts." (PMID 32614141, 2020). "High TDRD1 expression was strongly correlated with better PFS but it is currently unknown what its functional role is in cancer other than strong association with ERG expression in prostate cancer." (PMID 33374923, 2020). "The ERG interactome, including ERG-associated long-range chromatin, is a collaborative component of higher-order AR-associated chromatin structure and is involved in co-regulating subtypes of AR target genes in prostate cancer." (PMID 32634370, 2020). "However, the biological impact of aberrantly expressed ERG in prostate cancer progression and the underlying mechanisms are still unclear." (PMID 31143708, 2019). "Previous studies showed that prostate cancers could be grouped by various somatic mutations including TMPRSS2:ERG fusions and PTEN, 3p13, 5q21 and 6q15 genomic deletions." (PMID 30823906, 2019). "Increased ROCK1 expression was associated with TMPRSS2:ERG fusion positive prostate cancers." (PMID 31557128, 2019). "Thus, a recent study showed in a group of patients with metastatic castration-resistent prostate cancer treated with docetaxel chemotherapy, those with ERG+ primary tumors have a two times increased risk of therapy resistance than those with ERG- tumors." (PMID 31366128, 2019). "To evaluate whether BCAR1 expression is associated with ERG rearrangements in prostate cancers, we used pre-existing data on ERG status obtained by FISH in 5379 cancers and by IHC in 8421 tumors for which BCAR1 staining was also available." (PMID 29304771, 2018). "TMPRSS2:ERG gene aberration may be a novel marker that improves risk stratification of prostate cancer before definitive cancer therapy, but studies have been inconclusive." (PMID 27377958, 2016). "The mutual exclusive expression pattern suggests that association of ERG and miR-205 in human prostate cancers might be through an indirect mechanism." (PMID 27191272, 2016). "Furthermore, co-immunoprecipitation assays showed that endogenous ERG associates with speckle-type POZ protein (SPOP) ubiquitin ligase in LNCaP prostate cancer cells (see also Section 7)." (PMID 27208692, 2016). "This study underlines an important function for miR-449 in ERG-associated prostate cancer." (PMID 26988912, 2016). "Furthermore, we demonstrate that knockdown of TRIM25 with the same siRNAs causes increased protein levels of ERG in 22Rv1 prostate cancer cells that express ERG-V5 from a stably integrated expression vector." (PMID 27626314, 2016).
prostate carcinoma (continued). "Two established molecular subtypes are identified by high expression of the ERG oncoprotein, due to structural DNA alterations that encode for fusion transcripts in approximately 1⁄2 of prostate cancers, and over-expression of SPINK1, which is purportedly found only in ERG-negative tumors." (PMID 26172920, 2015). "Interestingly, it was recently shown, that only 5 of 23 (21.7%) analyzed prostate cancers from patients with a G84E mutation had an ERG fusion as compared to about 50% in unselected cohorts." (PMID 25825985, 2015). "To evaluate whether VEGFR-1 expression is associated with ERG status in prostate cancers, we used data from previous studies." (PMID 25894226, 2015). "Finally, expression of ERG in high-grade PIN was associated with a higher chance of developing prostate cancer at subsequent biopsies." (PMID 25243131, 2014). "Notably, an increase in the abundance of transcripts encoding full-length ERG was shown to correlate with less favorable outcomes in prostate cancer patients." (PMID 25988147, 2014). "Another issue worth mentioning regarding ERG is that, ERG gene rearrangements have been previously associated with specific histopathological features and detected more frequently in some morphologic variants of prostate cancer than others." (PMID 24027643, 2013). "The synergistic effects of AKT activation, overexpression of ERG and AR in basal cells closely recapitulated the histological and molecular features of human prostate cancer, with loss of basal cells and expansion of malignant luminal cells expressing PSA and AMACR." (PMID 23852643, 2013). "AR stimulates the expression of TMPRSS2: ERG, a common gene fusion associated with prostate cancer." (PMID 23466879, 2013). "Moreover, this study associates ERGIC1 and TMED3 expression with ERG oncogene expression, supporting their potential in the management of prostate cancer." (PMID 22761906, 2012). "More importantly, both studies demonstrated that transient androgen treatment resulted in induction of TMPRSS2: ERG fusion in prostate cancer cells, suggesting that androgen may play an important role in prostate cancer predisposition." (PMID 23272087, 2012). "It is reasonable to speculate that mutations contributing to prostate cancer progression may influence ERG protein stability." (PMID 22860005, 2012). "To determine whether Nkx3.1 down-regulation was functionally linked to ERG over-expression, we examined the level of Nkx3.1 in prostate cancer cells upon modulation of ERG." (PMID 20479932, 2010). "We envisage that ERG fusion-positive prostate cancer cells are susceptible to energy stress and the PGC1α-Sirt1 axis might provide survival benefits to tumors by activating antioxidant and metabolic functions of ERG fusion." (PMID 35508713, 2022). "Aberrant levels of inflammatory mediators that changed with ERG expressions have also been discovered, and the imbalance of inflammatory mediators might impact the progression of ERG-positive prostate cancer with some loss of immune capability involving HLA-DMB molecule and CD3+ cells." (PMID 35326519, 2022). "Studies have linked TMPRSS2 to prostate cancer via a chromosomal translocation resulting in the fusion of the TMPRSS2 promoter-enhancer with the Erythroblast Transformation Specific (ETS) transcription factors ETS-related gene (ERG) and ETS translocation variant 1 (ETV1)." (PMID 32974166, 2020). "Additionally, AR transcriptional activity is frequently co-opted by gene fusion events during prostate cancer (PCa) development and progression, as exemplified by AR-dependent ERG overexpression caused by fusion of the ERG gene body to the AR-regulated TMPRSS2 promoter." (PMID 25908785, 2015). "Thus, the frequently observed loss of NKX3.1 in prostate cancer may significantly contribute to the activation of ERG protooncogene." (PMID 24418414, 2014).
prostate carcinoma (continued). "As the TMPRSS2:ERG gene fusion was detected in one out of two Gleason 6 cultures tested, and is associated with lethal prostate cancer, further study of larger samples of prostate cancer stem cells from different classes of therapy-resistant and Gleason 6 tumors is warranted." (PMID 18492237, 2008). "The TMPRSS2:ERG gene fusion is a truncal oncogenic event in a large subset of prostate cancers, yet its clinical relevance has remained unclear." (PMID 41837288, 2026). "In patients with recurrence, there was an increased expression of ERG and ESR1, which is linked to aggressive prostate cancer." (PMID 40691608, 2025). "SPOP has been reported to specifically interact with ERG, promoting its ubiquitination and degradation through WT-SPOP, which negatively regulates ERG-mediated prostate cancer cell migration and invasion." (PMID 40771930, 2025). "Among fusion events, ERG was the most frequent gene partner (2.7% overall), driven by its high prevalence in prostate cancer (36.2%)." (PMID 40711866, 2025). "The TMPRSS2:ERG fusion represents the most common genomic alteration in prostate cancer, occurring in almost half of all prostate cancers especially in younger patients." (PMID 40554389, 2025). "The ERG gene serves as a prostate cancer marker, and the ERG-TMPRSS gene fusion is one of the most common gene rearrangements in prostate cancer." (PMID 39988626, 2025). "Lineage tracing in mice identifies a subpopulation of basal cells that express Tmprss2 and Nkx3 as the origin of ERG-driven prostate cancer." (PMID 40858905, 2025). "Other mutations and copy number alterations were less frequent than ERG fusions in the prostate cancer TCGA cohort." (PMID 40332161, 2025). "Another alternative splicing decision relevant for ERG expression in prostate cancer involves cassette exons 7 and 7b." (PMID 40190563, 2025). "By analyzing the expression profiles of RNA biomarkers such as ERG, PCA3, and SPDEF in exosomes, this technology can effectively distinguish high-risk prostate cancer (Gleason score ≥ 7) from low-risk cases." (PMID 40277513, 2025). "Prostate cancers with high MCOLN2 mRNA expression were more frequently (69.9% of cases) positive for ERG fusions than cancers with low MCOLN2 mRNA expression (26.5% of cases positive, Fisher’s exact test p = 0.0001)." (PMID 40332161, 2025). "The mechanism by which ERG expression reversed the role of MTAP in prostate cancer cells is unclear and cannot be determined from our data." (PMID 40554389, 2025). "indicates that ERG can promote the expression of YAP in prostate cancer cells by influencing the H3K9/14 acetylation of the YAP promoter." (PMID 39963114, 2025). "Studies have shown that the elevated expression of the ERG oncogene in prostate cancer patients is due to its fusion with transmembrane protease serine 2 (TMPRSS2)." (PMID 40243658, 2025). "TMPRSS2 is one of the target genes of the AR, and when androgens stimulate TMPRSS2-ERG fusion-positive prostate cancer cells, a significant increase in ERG expression can be observed." (PMID 39963114, 2025). "Previous studies have indicated that ERG promotes tumor initiation and progression in prostate cancer, lung cancer, and acute myeloid leukemia (AML); however, its specific effects in MM remain inadequately understood." (PMID 40741330, 2025). "Our findings demonstrate the importance of PTEN and TMPRSS2:ERG fusion and tumour molecular subtyping in prostate cancer precision medicine." (PMID 40165885, 2025). "In prostate cancer, ERG has been shown to repress the transcription of the tumor suppressor PTEN, potentially activating the PI3K/Akt pathway and increasing angiogenesis, invasion, and metastasis." (PMID 40666093, 2025). "In 2005, researchers identified the TMPRSS2 (transmembrane serine protease 2)-ERG (ETS-related gene) fusion gene in prostate cancer for the first time." (PMID 40584293, 2025).